OPRD1 (opioid receptor delta 1)
Diseases named in the same sentence as OPRD1 in open-access papers:
OPRD1 is named in the same sentence as 47 diseases in open-access papers, as found by Europe PMC text mining. Sharing a sentence is not in itself a finding about the gene and the disease. The quoted sentences say what the papers report.
opioid dependence (5 papers, 2013 to 2024). "Specifically, these studies link OPRD1 variability to the response to pharmacological treatment for opioid dependence and the risk of addiction to opioids and cocaine." (PMID 39274402, 2024). "Indeed, we observed a significant association of the intronic OPRD1 SNP rs2236861 with opioid dependence in our European study population." (PMID 24086514, 2013).
Anxiety (4 papers, 2014 to 2024). Intense feelings of nervousness, tension, or panic often arise in response to interpersonal stresses. "The enkephalin system in amygdala is involved in emotional processing of states such as anxiety and stress and Oprd1 and Penk knock-out mice show increased anxiety and depressive like behaviors in a variety of tests." (PMID 30250435, 2018). "The related δ-opioid receptor also participates in pain-reducing pathways, and knockout studies demonstrate that mice deficient for μ - and δ-opioid receptors exhibit opposing emotional phenotypes, in which Oprd1−/− animals have elevated anxiety." (PMID 24765068, 2014). "Based on previous studies demonstrating that Penk knockout (KO) mice show increased anxiety behavior and aggression, and Oprd1 KO mice show increased depression-like behavior, DOR has been considered to be a promising target for antidepressants and anxiolytics in addition to analgesics." (PMID 34630408, 2021).
Obesity (4 papers, 2015 to 2024). Accumulation of substantial excess body fat. "Moreover, a genetic variant in OPRD1 has been associated with obesity and appetite regulation, and this locus interacts with sex45." (PMID 38918439, 2024). "Interestingly, other variants also known to influence reward/addiction associated processes or eating related behaviour such as OPRD1, BDNF, GHRL and CNR1, also revealed evidence of being associated with overweight/obesity or development to an adverse metabolic status." (PMID 26445370, 2015).
Alzheimer disease (3 papers, 2017 to 2024). A progressive, neurodegenerative disease characterized by loss of function and death of nerve cells in several areas of the brain leading to loss of cognitive function such as memory and language. "OPRD1 encodes the delta-opioid receptor, important for cognitive function and regulating reward pathways, and has previously been associated with Alzheimer’s disease and opioid addiction." (PMID 38918439, 2024). "Genetic diversity and DOR expression levels of OPRD1 are associated with a variety of diseases, including substance abuse and addiction, anorexia nervosa (AN), obesity, and Alzheimer's disease (AD)." (PMID 35299869, 2022).
Depression (3 papers, 2013 to 2023). "Depression is associated with neuronal development and Oprd1 signaling." (PMID 24152443, 2013).
neuroblastoma (3 papers, 2017 to 2024). Neuroblastoma (NB) is the most common solid, extracranial childhood tumor. "A common OPRD1 variant is shown to be associated with the accumulation of amyloid precursor protein in human neuroblastoma cells." (PMID 28253273, 2017). "In studies involving neuroblastoma cells, Oprd1 is transcriptionally active in undifferentiated cells but becomes inactive during neuronal differentiation." (PMID 39199314, 2024). "Without methylation, the Oprd1 promoter in neuroblastoma cells remains accessible." (PMID 39199314, 2024).
alcohol dependence (2 papers, 2013 to 2024). Physical and psychological dependence on alcohol. "Numerous candidate gene studies have implicated OPRD1 in addiction, including opioid, cocaine, and alcohol dependence." (PMID 38177348, 2024).
dependence (2 papers, 2013 to 2021). "Opioid receptor delta 1; involved in opioid dependence and aspects of nicotine action." (PMID 33828466, 2021).
eating disorder (2 papers, 2009 to 2024). A broad group of psychological disorders with abnormal eating behaviors leading to physiological effects from overeating or insufficient food intake. "Finally, beyond addiction, the role of the Oprm1 and Oprd1 genes in impulsivity has implications for understanding and treating attention deficit hyperactivity disorder, eating disorders, gambling and other disorders of impulse control." (PMID 19198656, 2009).
substance abuse (2 papers, 2020 to 2021). The use of a drug for a reason other than which it was intended or in a manner or in quantities other than directed. "Some of us previously investigated involvement of eight genes in the opioid system (OPRD1, OPRK1, OPRL1, OPRM1, PDYN, PENK, PNOC, and POMC) and their potential effects on substance abuse." (PMID 34440333, 2021).
type 2 diabetes mellitus (2 papers, 2018 to 2020). A type of diabetes mellitus that is characterized by insulin resistance or desensitization and increased blood glucose levels. "Examples of predicted applicable diseases of sinomenine are adiposity and type II diabetes mellitus, implying that sinomenine is effective for treatment of adiposity and type II diabetes mellitus based on the target proteins: GAA, OPRM1, OPRD1, OPRK1." (PMID 30046160, 2018).
adenoma (1 paper, 2024). A neoplasm arising from the epithelium. "Noteworthy, the numbers of RNA interactors of some MP-RNAs (WDR62, TGFBR3, RN7SL5P, RMRP, MIR663AHG, AJ009632.2, CDKL1, OPRD1, PLOD1, AL117692.1, ATP13A2, EPB41) in cancer tissue were significantly increased compared with that in paracancer and adenoma." (PMID 38773399, 2024).
anorexia nervosa (1 paper, 2017). A disorder most often seen in adolescent females characterized by a refusal to maintain a minimally normal body weight, an intense fear of gaining weight, a disturbance in body image, and, in postmenarcheal females, the development of amenorrhea. "Additionally, a number of SNPs within the OPRD1 gene were significantly associated with anorexia nervosa." (PMID 28604785, 2017).
colorectal cancer (1 paper, 2025). A primary or metastatic malignant neoplasm that affects the colon or rectum. "This study evaluated the association of OPRM1 (rs1799971 and rs510769) and OPRD1 (rs2236861) polymorphisms with pain severity, opioid efficacy, and ADRs in Chilean colorectal cancer patients." (PMID 40006034, 2025). "This study explored the genetic variability in opioid receptor genes (OPRM1 and OPRD1) and their association with pain and adverse drug reactions (ADRs) in colorectal cancer patients in a Latin American Mestizo sample (Chileans)." (PMID 40006034, 2025). "Based on this background, this study hypothesizes that polymorphisms in OPRM1 and OPRD1 influence the response to opioids, thereby conditioning their therapeutic effectiveness and toxicity in patients with advanced-stage colorectal cancer." (PMID 40006034, 2025). "Background/Objectives: Pain management in colorectal cancer is influenced by genetic variability in opioid receptor genes (OPRM1 and OPRD1), potentially affecting opioid efficacy and adverse drug reactions (ADRs)." (PMID 40006034, 2025).
drug dependence (1 paper, 2013). "In the present study, we further analyzed the interactive effect of OPRM1, OPRD1, and OPRK1 variants on alcohol or drug dependence using a pattern discovery-based method." (PMID 24533225, 2013). "Considering the close biological interaction of the three receptors, we hypothesized that variation in their genes (OPRM1, OPRD1, and OPRK1) might have joint effects on risk for alcohol or drug dependence." (PMID 24533225, 2013).
Dysmenorrhea (1 paper, 2017). Pain during menstruation that interferes with daily activities. "The endogenous system of opioid receptors (OPRM1 and OPRD1) is well known for its analgesic potential; XGDP may treat dysmenorrhea through regulating central analgesic effects." (PMID 29234428, 2017).
epilepsy (1 paper, 2021). A brain disorder characterized by episodes of abnormally increased neuronal discharge resulting in transient episodes of sensory or motor neurological dysfunction, or psychic dysfunction. "There are no previous studies directly reporting associations between the other 2 key targets (ADOR1, OPRD1) and epilepsy." (PMID 33407404, 2021).
liver fibrosis (1 paper, 2025). "In contrast, Ppp2r2b, Sgpp2 (P < 0.0001), and Oprd1 (P < 0.001) were significantly upregulated in the WD liver fibrosis model." (PMID 40557038, 2025).
migraine (1 paper, 2023). "Of the 25 overlapping genes/loci, 6 genes/loci were associated with more than 2 phenotypes in HPGDB (COMT, OPRD1, IL1A, IL1B, TSPAN2/NGF, GDF5), and 15 genes were associated with migraine." (PMID 37144689, 2023).
psychosis (1 paper, 2020). "Five genes, DRD2, DRD3, HTR2A, OPRD1 and HTR7, are found shared by psychosis network and antipsychotics network." (PMID 32273551, 2020).
cancer (8 papers, 2010 to 2025). A tumor composed of atypical neoplastic, often pleomorphic cells that invade other tissues. "This highlights the need for further research to investigate the impact of OPRD1 variants on opioid response in the context of cancer-related pain." (PMID 40006034, 2025). "In addition, the expression of OPRD1 in cancer tissues was also higher than that in adjacent tissues, with an insignificant difference." (PMID 35422890, 2022). "Previous studies have identified OPRD1 as being upregulated in cancer and use of opioid-based analgesia during cancer treatment has been correlated with increased metastasis and decreased survival, though the mechanisms underpinning the role of OPRD1 in metastasis are largely unknown." (PMID 37575281, 2023). "TIMER database was used for pan‐cancer analysis of different pain genes (Nav1, EHMT2, SP1, SLC6A4, COMT, OPRM1, OPRD1, CYP2D6, and CYP3A4)." (PMID 38352696, 2024). "Moreover, we also found some genes that have not been identified as tumour-associated genes by Cancer Gene Census also encode potential neoantigens, such as MUC4, FAM194B, OPRD1 and FRG1." (PMID 28484631, 2017).
tumor (5 papers, 2017 to 2024). "Increased TMB and FGA are both correlated with upregulation of OPRD1 in LUAD, consistent with both TMB and FGA magnifying the pro-tumor opioid-survival association in LUAD." (PMID 40909996, 2024). "The results are consistent with the increase in OPRD1 expression identified by single-cell transcriptomics in tumor-escaping cells, and suggest that the δ opioid receptor plays a critical, yet underappreciated role in the earliest phases of metastasis." (PMID 37575281, 2023). "DESeq analysis identified increased expression of OPRD1 in both escaping and amoeboid cells when compared with epithelial cells, indicating OPRD1 is upregulated upon tumor escape and maintained during amoeboid invasion." (PMID 37575281, 2023). "Together, these results show that naltrindole-mediated OPRD1 inhibition results in decreased spheroid growth and prevents tumor escape." (PMID 37575281, 2023). "The DE analysis identified an upregulation of OPRD1 in both escaping and amoeboid cells when compared with epithelial cells, indicating that the δ opioid receptor supports tumor escape." (PMID 37575281, 2023). "To investigate whether OPRD1 signaling, and therefore our observation of increased OPRD1 expression, holds a functional role in tumor escape, we carried out a 3D spheroid invasion assay in the presence of naltrindole, a selective δ-opioid receptor antagonist." (PMID 37575281, 2023). "Therefore, there is an energy competition between tumor cells and immune cells, and OPRD1 may act as a regulatory role." (PMID 35422890, 2022). "Our study revealed that the expression levels of NAV1, EHMT2, SP1, SLC6A4, OPRD1, and CYP3A4 between the normal and tumor were statistically significant." (PMID 38352696, 2024).
neurodegenerative disease (1 paper, 2022). A disorder of the central nervous system characterized by gradual and progressive loss of neural tissue and neurologic function. "Common variants of OPRD1 have also been found to be associated with neurodegenerative diseases." (PMID 35345408, 2022).
OPRD1 also shares sentences with these, for which no sentence is quoted: infection (8 papers); cystic fibrosis (4); heroin dependence (3); malignant melanoma (2); schizophrenia (2); attention deficit-hyperactivity disorder (1); autism (1); breast carcinoma (1); cannabis dependence (1); chronic lung infections (1); co-infection (1); cocaine dependence (1); colitis (1); coronary artery disease (1); gastric cancer (1); hepatocellular carcinoma (1); itch (1); morphine dependence (1); neutropenia (1); Pan (1); pancreatic carcinomas (1); pneumonia (1); psychiatric disorder (1); respiratory infections (1).